RBMXL3 (RBMX like 3)
Description:
RNA-binding protein involved in glucocorticoid regulation of pulmonary surfactant protein B (SFTPB) mRNA stability.
Synonyms: CXorf55; FLJ40249
Tractability: No criterion of Open Targets' tractability assessment is met for any kind of drug.
Gene: Protein-coding gene on chromosome X (115,189,410 to 115,192,868, forward strand). Ensembl gene ENSG00000175718.
Gene Ontology:
Molecular function: RNA binding; mRNA binding; snRNA binding; nucleic acid binding
Cellular component: precatalytic spliceosome
Homologues: Orthologues: chimpanzee RBMXL3 (93% identical), mouse Rbmxl2 (22% identical), rat Rbmxl2 (21% identical). Paralogues in human: RBMXL2 (24% identical), RBMX (21% identical), RBMXL1 (19% identical), RBMY1B (15% identical), RBMY1D (15% identical), RBMY1E (15% identical), RBMY1A1 (15% identical), RBMY1F (15% identical), RBMY1J (15% identical), CIRBP (7% identical), HNRNPA3 (7% identical), DAZAP1 (7% identical), and 24 more.
Diseases named in the same sentence as RBMXL3 in open-access papers:
RBMXL3 is named in the same sentence as 4 diseases in open-access papers, as found by Europe PMC text mining. Sharing a sentence is not in itself a finding about the gene and the disease. The quoted sentences say what the papers report.
neuroblastoma (2 papers, 2021 to 2025). Neuroblastoma (NB) is the most common solid, extracranial childhood tumor. "In 58 whole exome sequencing (WES) and 48 whole transcriptome sequencing (WTS) samples of MYCN non-amplified neuroblastoma (NB), recurrent mutations were observed in genes like MUC4 and RBMXL3." (PMID 39823827, 2025).
Azoospermia (1 paper, 2025). Absence of any measurable level of sperm,whereby spermatozoa cannot be observed even after centrifugation of the semen pellet. "Similarly, in individuals with the RBMXL3 mutation, our findings align with previous studies, demonstrating an association with SCOS and azoospermia." (PMID 39932629, 2025).
Sertoli Cell-Only Syndrome (1 paper, 2025). A type of male infertility in which no germ cells are visible in any of the biopsied SEMINIFEROUS TUBULES (type I) or in which germ cells are present in a minority of tubules (type II). "Mutations in RBBP7 and RBMXL3 led to Sertoli cell-only syndrome (SCOS)." (PMID 39932629, 2025).
RBMXL3 also shares sentences with these, for which no sentence is quoted: Infertility (1 paper).